CD4 (CD4 molecule)
Diseases named in the same sentence as CD4 in open-access papers (continued):
Sharing a sentence is not in itself a finding about the gene and the disease.
colon carcinoma (continued). "In addition, FAM110B also acts as an important hub gene in the immune microenvironment of colon cancer cells, and its expression level is negatively correlated with tumor purity and positively correlated with the infiltration of CD4 T cells, macrophages, neutrophils and dendritic cells." (PMID 39170745, 2024). "In summary, our research suggests that miRNA regulation of genes plays an important role in CD4 memory resting cells, macrophages.M2, and Mast.cell.activated cells and cytokine and cytokine receptor signaling pathways, which makes it closely related to the development and prognosis of colon cancer." (PMID 37465677, 2023). "In addition, KLF15 was shown to be positively linked with CD4+ T cell and macrophage levels in colon cancer patients but not in rectal cancer patients." (PMID 35345512, 2022). "Thus, we speculated that MUC4 mutation might positively regulate CD4 and CD8 T cell while negatively regulate Tregs in colon cancer." (PMID 33714943, 2021). "infection, which may negatively affect memory-activated CD4+ T cell infiltration in colon cancer." (PMID 34938284, 2021). "Moreover, in a randomized controlled trial (RCT), β-carotene (30 mg/d) supplementation for 3 months in subjects with colonic polyps or colon cancers increased CD4 count only in cancer patients who had a lower percentage of CD4 than in patients with polyps and in controls." (PMID 29861829, 2018). "The results further confirm that ACE can increase the proportion of T-lps in the peripheral blood of colon cancer patients, especially CD3+ and CD4+ T cells, regulate the balance of Th1/Th2 cells, and thus exert anti-tumor effects." (PMID 40417009, 2025). "Colon cancer showed a positive correlation between SIRT1 and CD4+ T cells (r = 0.342), CD8+ T cells (r = 0.25), macrophages (r = 0.253), and neutrophils (r = 0.216), which is promising." (PMID 41020376, 2025). "We found that mMGL1 deletion contributed to the increased percentage of CD4+ and CD8+ T cells in the circulation and lamina propria while downregulating the MDCs and M‐MDSCs recruitment in the lamina propria of colon tumors." (PMID 40033767, 2025). "It has been experimentally proven that hematopoietic cell marker proteins like CD4 and CD45 can be transferred via trogocytosis from tumor infiltrating immune-cells to colon cancer cells." (PMID 41181711, 2025). "Two distinct TCRs specific to PIK3CAN345K, restricted by HLA-class II pair DPB1*04:01/DPA1*01:03, were identified in a patient with colon cancer, following independently a TIL screen and an IVS of memory CD4 + T cells from the peripheral blood." (PMID 41410746, 2025). "CD4+ and CD8+ T cell levels are higher in patients with MSI-high colon cancer than in those with MMS." (PMID 39726813, 2024). "In addition to colon cancer severity and fatality, its prognosis is influenced by other factors, including the immune response, as microenvironments play a crucial role in tumor-cell immune cell infiltration particularly macrophages, and T cells, including CD4+ and CD8+." (PMID 38894777, 2024). "Previous studies have shown that IL-17 in colon tumours is produced by CD8 + T cells (Tc17), CD4 + T cells (Th17) and γδTCR + T cells (γδT17)." (PMID 37211606, 2023). "Among I-IV colon cancer, the highest levels of CEA, CA199, NLR, D-dimer, CD4+ and CD4+/CD8+ ratio were found in patients with Stage-IV colon cancer, while the level of CD8+ was the lowest (P<0.05)." (PMID 37492300, 2023). "Conversely, we found that both CD3+CD4+ and CD3+CD8+ T cells are significantly increased in ApcMin/+; p16cis/cis colon tumors (average of 17.8% and 7.5%, respectively)." (PMID 37143122, 2023). "The TIMER online tool was utilized to perform correlation analysis between TOMM34 expression and infiltration of six types of immune cells in colon cancer, including B cells, CD8+ T cells, CD4+ T cells, macrophages, neutrophils and dendritic cells." (PMID 36845719, 2023).
colon carcinoma (continued). "Consistent with the previous report, we detected similarly low frequencies of CD3+CD4+ and CD3+CD8+ T cells in ApcMin/+ colon tumors (average of 2.3% and 0.6%, respectively)." (PMID 37143122, 2023). "Among them, the highest levels of CD4+ and CD4+/CD8+ ratio and the lowest level of CD8+ were found in patients with Stage-IV colon cancer(P<0.05)." (PMID 37492300, 2023). "To evaluate which immune cell populationswere mediating antitumor efficacy, we administered depletion antibodiesspecific for CD4, CD8α, or colony stimulating factor-1 receptor(CSF1R) to MC38 colon carcinoma-bearing mice prior to starting polymertherapy." (PMID 36313164, 2022). "Dual CTLA- and PD-L1 blockade exert synergistic inhibitory effects on growth and metastasis of the orthotopic CT26 colon tumors by increasing CD8+ and CD4+ T cells." (PMID 35936516, 2022). "The frequencies of a CD4(+) effector (T9) and a CD8(+) effector (T18) cluster were significantly higher in patients with colon tumor than patients with rectal tumor on days 1 and 3 after surgery." (PMID 35185893, 2022). "The colon cancer group showed a marked increase in serum levels of CA19.9, CEA, AFP, TNF-α, IL-1β, and colon DNA-fragmentation matched with a decrease of CD4+ compared with the control group." (PMID 36294905, 2022). "In colon cancer, the B-cell, macrophage, neutrophil, and dendritic-cell levels are downregulated after ARHGAP4 gene knockout; the levels of CD8+ and CD4+ T cells, neutrophils, and dendritic cells are upregulated after the amplification of the ARHGAP4 gene." (PMID 35847897, 2022). "The expression of ARHGAP4 was highly correlated with the infiltration of CD4+ T cells in CRC and with dendritic cells in READ.In colon cancer, after ARHGAP4 gene knockout, the levels of B cells, macrophages, neutrophils, and dendritic cells are downregulated." (PMID 35847897, 2022). "In a mouse model, GNAI1 and GNAI 3 suppressed DSS-plus-azoxymethane-induced colon tumor development, whereas the expression of GNAI2 in CD11c+ cells and interleukin-6 (IL6) in CD4+/CD11b+ dendritic cells appeared to promote these effects." (PMID 35743732, 2022). "For example, low dose cisplatin and oxaliplatin increase the number of circulating CD4+ and CD8+ T cells, while high dose regimens decrease the size of lymphocyte in a mouse model of colon cancer." (PMID 36703971, 2022). "The correlation between CD4+ T cells and RPS14 (correlation = −0.5) was the highest in colon cancer while CD8+ T and RPS2 (correlation = −0.53) was the highest in rectal cancer." (PMID 35127345, 2022). "Similarly, in colon cancer, regulatory T cells (Tregs), which inhibit immunity and promote tumorigenesis, were up-regulated and the infiltration of activated memory T cells CD4 (CD4+ T cells) was down-regulated in the group with high expression of the immune gene CD34/CD276." (PMID 35590394, 2022). "The proliferation of CD4+ and CD8+ T cells was observed in the spleen and blood in colon cancer under increased ATP levels after inhibition of CD39." (PMID 34299098, 2021). "The expression of IRF3 in patients with colon cancer was negatively correlated with the infiltration level of B cells, CD8+ T cells, and macrophages, and positively correlated with the infiltration of CD4+ T cells." (PMID 34488791, 2021). "In summary, these results indicate that the combination treatment of CQ and PD-1 siRNA can enhance the infiltration of CD4+ and CD8+ T lymphocytes in colon cancer tissues." (PMID 34295341, 2021). "In a colon carcinoma model, endogenous IL-33 promoted IFN-γ expression by both CD4+ and CD8+ T cells, increased CD8+ T cell infiltration over Treg cells and augmented CD8+ T cell-mediated antitumor responses." (PMID 33329534, 2020). "The expression of CBXs were significantly correlated with the infiltration of diverse immune cells, including six types of CD4+ T cells, macrophages, neutrophils, B cells, CD8+ T cells, and dendritic cells in colon cancers and rectal cancers." (PMID 33014884, 2020).
colon carcinoma (continued). "In the peripheral blood, 18.09% of CD4+ TEMRA/TEFF cells were found in colon cancer and 81.91% in rectal cancer, while 64.06% of CD8+ TEMRA/TEFF cells were found in colon cancer and 35.96% in rectal cancer." (PMID 33584715, 2020). "Previous studies have reported that moxibustion increased the number of CD4+T and CD8+ T cells in the blood of patients with colon cancer metastasis to the liver, improving the immune status of patients." (PMID 33456484, 2020). "In this study, immune-related genes were evaluated in tumor-infiltrating CD4+ and CD8+ T cells in colon cancer." (PMID 32571262, 2020). "A series of bioinformatics analyses were conducted to identify and characterize DEGs related to CD4+ and CD8+ T cells in colon cancer tissues." (PMID 32571262, 2020). "This study showed that the expression of CD4+ T cells, CD8+ T cells, and IFN-γ was down-regulated, while that of IL-10 and TGF-β1 was up-regulated in liver metastases from colon cancers in mice." (PMID 32104586, 2020). "The expression levels of CD4+ T cells, CD8+ T cells, and IFN-γ were down-regulated, whereas those of IL-10 and TGF-β1 were up-regulated in liver metastasis from colon cancer in mice." (PMID 32104586, 2020). "(a) Proportion of CD4+ and CD8+ T cells in REP expanded TILs derived from normal/inflamed or tumor prostate tissue and metastasis of colon cancer or of melanoma." (PMID 31601268, 2019). "This was similar to the in vivo findings that administration of 50 μg recombinant IL-24 promoted CD4+ T cells response, especially increased IFN-γ production in colon cancer mouse model." (PMID 31921658, 2019). "We also checked the CD45+, F4/80+, CD4+, CD19+ cell populations in the tumours of WT or AMPKα2−/− mice at day 14 after colon cancer cell injection." (PMID 30636376, 2019). "PBMCs from colon cancer patients expanded with VIPhyb and idelalisib resulted in enhanced PSI in CD4+ T cells." (PMID 30400835, 2018). "Soluble colon cancer mucins containing mucins MUC1/2 inhibited IL-2 mRNA expression and secretion of CD4+." (PMID 29661177, 2018). "To assess the frequency of Tn and Tm cells in PBMCs from colon cancer patients, we quantified the CD4+CD45RA+ T cells, CD4+CD45RO+ T cells, CD8+CD45RA+ T cells and CD8+CD45RO+ T cells." (PMID 29230377, 2017). "Both CD4+ and CD8+ T cells were targeted by colon cancer specific mAb conjugated SEA, to lyse colon cancer in vivo." (PMID 21176167, 2010). "To find a way to evaluate the CD4+CD25+/CD4+ in antitumor immunotherapy targeting CD4+CD25+ TR cells, we analyzed the proportion in peripheral blood and spleen lymphocytes in normal or C26 colon-carcinoma-bearing mice by flow cytometry." (PMID 15679891, 2005). "In order to find a way to evaluate the CD4+CD25+ TR cells in tumor-bearing mice, we analyzed CD4+CD25+ subset in peripheral blood and spleen lymphocytes from normal or C26 colon-carcinoma-bearing mice by flow cytometry." (PMID 15679891, 2005). "Additionally, administration of IL‐24 reconfigured the TME (tumor microenvironment) in murine colon cancer models, with a higher percentage of CD45+ CD4+ and CD45+ CD8+ cells and a decrease in CD45+ CD4+ Foxp3+ cells, suggestive of a type I immune response." (PMID 40338095, 2025). "Furthermore, combined treatment with OX40 and GITR ligand fusion proteins enhanced both CD4+ and CD8+ T cell activation and antitumor activity in CT26 colon cancer–bearing mice." (PMID 40178907, 2025). "The levels of cfDNA components derived from CD4 + T cells and intestinal cells detected by the LABS could be promising markers themselves to enhance the sensitivity and specificity for colon cancer detection and screening." (PMID 38877540, 2024). "Therefore, the BRAF(V600E) mutation was associated with CTHRC1 expression, and both were correlated with immune cell infiltration including CD4+ T cells, CD8+ T cells, and neutrophils, in colon cancer and thyroid cancer patients." (PMID 39052013, 2024).
colon carcinoma (continued). "IL-21 is produced by CXCL13 + CD4 + T cells in human colon cancer, liver cancer, and non-small cell lung cancer." (PMID 38833177, 2024). "Deconvolution algorithms revealed significant differences in infiltrated immune cells between left-sided colon cancer (LCC) and right-sided colon cancer (RCC), including dendritic cells, neutrophils, natural killer (NK) cells, CD4 and CD8 T cells, and M1 macrophages (P < 0.05)." (PMID 39267963, 2024). "The tumor growth inhibitory effects of CDIM/NR4A1 antagonists were observed in immune competent mice bearing MC-38 mouse colon cancer cells and this was accompanied by modest changes in CD8+ and CD4+ T-cells and Treg cells in TILs and a significant decrease in CD4+/CD8+ ratios." (PMID 37847301, 2023). "Furthermore, the Bifidobacterium strain improves antitumor immune responses in mice with colon cancer by raising CD4+ and CD8+ T cells and NK cells and the CD4+/Treg, CD8+/Treg and effector CD8+/Treg ratios." (PMID 36983053, 2023). "Moreover, Bifidobacterium strain enhances the efficacy of anti-tumor immune responses in colon cancer-bearing mice by increasing CD4+ and CD8+ T-cells, NK cells, and the CD4+/Treg, CD8+/Treg, and effector CD8+/Treg ratios." (PMID 35892821, 2022). "Under the colonic cancer state, F. nucleatum could promote the recruitment of myeloid immune cells (CD11B+ cells) and inhibit the CD4+T cells." (PMID 35631034, 2022). "In mouse models of colon carcinoma, endogenous IL-33 overcame the pro-tumorigenic effect of Treg by increasing IFN-γ production of tumor-infiltrating CD4+ and CD8+ T cells, as well as the accumulation of these infiltrating CD8+ T cells, exerting their anti-tumor effect." (PMID 34209038, 2021). "Among them, six types of tumor-infiltrating immune cells were positively correlated with high mRNAsi in colon cancer, namely, CD8+ T cells, resting NK cells, activated memory activated CD4+ T cells, follicular helper T cells, and resting and activated dendritic cells." (PMID 34568334, 2021). "CD47-SIRPα blockade by anti-CD47 antibody enhances antigen cross-presentation by DCs and promotes T cell priming, consequently, CD8+ T cells, but not CD4+ T cells, mediate killing on colon cancer cells." (PMID 34512146, 2021). "This is also reflected by the different immune phenotype observed with lower numbers of CD4 single positive cells, CD4 Treg cells, and higher mDC, pDC, NKT cells in therapy-naïve rectal cancer compared to colon cancer, suggesting a lower level of natural immune activation in rectal cancer patients." (PMID 34771707, 2021). "The antitumor activity by CD47 blockade enhances cancer cell clearance by both of phagocytes and T cells 26, 37, and anti-CD47 antibody enhances CD8+ T cells killing but not CD4+ T cell in colon cancer cells." (PMID 34512146, 2021). "Therefore, the increased CD4+ and CD8+ T cell frequencies by PPA1-DOX indicates that this conjugate is able to restore T cell function and enhance immune response in colon cancer." (PMID 34858817, 2021). "Our results clearly demonstrated that low-dose CTX selectively suppressed the number of IL-10- and TGF-β1-positive cells, increased the number of conventional CD4+ and CD8+ T cells in the spleen, and efficiently inhibited liver metastasis of murine CT26 colon-cancer cells." (PMID 32104586, 2020). "The chr22-38_28785274–29,006,793.1–miR-106a-5p-DDHD1 and chr22-38_28785274–29,006,793.1–miR-4319-GRHL1 axes may be related to CD4+ and CD8+ T cell infiltration in colon cancer." (PMID 32571262, 2020). "Additionally, the infiltration of B cells, CD4+ T cells, macrophages, neutrophils, and dendritic cells was kept in with CBX4 expression in colon cancer patients." (PMID 33014884, 2020). "Notably, more than 30% of CD4+ FOXP3+ Tregs in colonic tumors of BALB/c mice expressed ST2, versus 3% of CD4+ FOXP3- T cells, thus indicating that ST2 expression in the CD4+ T cell compartment was mainly restricted to FOXP3+ Tregs." (PMID 31165767, 2019).
colon carcinoma (continued). "Furthermore, the lymphocytes (CD4 and CD25) and cytokines are reported to be the novel therapies for colon cancer in humans." (PMID 29568324, 2018). "Additionally, in an ApcMin+ model of colon cancer, ApcMin/+/Cysltr1−/− mice tended to have fewer CD3+CD4+ T cells infiltrating polyps." (PMID 28410235, 2017). "Remarkably, the CD4/CD8 ratio, which indicates the immune state, is significantly lower in the tumor and peri-tumoral zone of CCR9−/−, suggesting that CCR9 expression controls the immune balance in colon cancer, and showing an enrichment of CD8+ T cells when CCR9 is absent." (PMID 40305493, 2025). "In this study, we designed DNA vaccines encoding multiple CD8+ T cell epitopes derived from the MC-38 colon carcinoma without (noHELP) or with universal- (uniHELP) or MC-38-derived (neoHELP) CD4+ T cell epitopes, and tested their immunogenicity and tumor control." (PMID 39040850, 2024). "The authors hypothesize that tumor progression was promoted in a setting of extensive CD4+ T-cell infiltration by microsatellite-unstable colon carcinoma cells that were lacking in HLA class II expression." (PMID 37046620, 2023). "According to the current research, administering LME to colon cancer-model rats significantly reduced their levels of AFP, CEA, and CA 19.9, as well as immune-inflammatory markers (TNF-α and IL-1β) matched with the development of apoptotic biomarker (CD4+), compared to the control group." (PMID 36294905, 2022). "Also, we conducted single-cell RNA-Seq analysis of syngeneic mouse colon cancer (MC38) over time and found that, as tumors progress, there is less CD40L expression on CD4+ T cells in the TME, suggesting that this signaling may be limited." (PMID 36073543, 2022). "In colon cancer, TIMP1 has higher expression levels in tumor tissues and lymph node metastases than in normal tissues, the expression level of TIMP1 in colon cancer is significantly positively correlated with CD4+T cells, macrophages, neutrophils and dendritic cells." (PMID 34552622, 2021). "In this study, the number of CD4+ and CD8+ T cells in the liver and spleen significantly decreased in the CLM group compared with those in the normal group, which showed that the cellular immunity of the liver and spleen decreased during the development of liver metastases from colon cancers." (PMID 32104586, 2020). "It has been demonstrated previously that IFN-γ can induce activation and expansion of MDSCs in colon cancer, and that activated MDSCs not only inhibit effector T cell activity/proliferation but also induce immunosuppressive CD4+CD25+Foxp3+ TReg cells from CD4+CD25− T cells." (PMID 22496728, 2012). "To test this hypothesis, we employed CT26, a murine colon cancer model with high CD8+ T cell infiltration, using mock- or ULBP2-transfected tumor cells to examine the impact of ectopic ULBP2 expression under T cell-modulatory conditions with anti-CD4, anti-CD25, and anti-CTLA-4 antibody treatments." (PMID 40558520, 2025). "Correlation analysis indicated that CEA, CA199, NLR, D-dimer and CD8+ were positively correlated with whether the patient had colon cancer (r=0.841, 747, 991, 889, 565, all P<0.05), but negative correlations were observed with CD4+ and CD4+/CD8+ ratio (r=-0.999, -0.994, all P<0.05)." (PMID 37492300, 2023). "Correlation analysis indicated that CEA, CA199, NLR, D-dimer and CD8+ were positively correlated with whether the patient had colon cancer (r=0.841, 747,991,889,565, all P<0.05), but negative correlations with CD4+ and CD4+/CD8+ ratio (r=-0.999, -0.994, all P<0.05)." (PMID 37492300, 2023). "IL-6 can be secreted by a large panel of different immune and non-immune cells, whereby lamina propria CD4+ T cells and, in particular, PU.1-driven Th9 cells, dendritic cells, and tumor cells could be identified as the main producers of this cytokine in colon tumors." (PMID 36428508, 2022).